LAG3 (lymphocyte activating 3)
Diseases named in the same sentence as LAG3 in open-access papers (continued):
Sharing a sentence is not in itself a finding about the gene and the disease.
tumor (continued). "In subsequent investigations, we examined the epigenetic modifications in tumor and normal tissues and found that the CpG motifs in the promoter regions of PD-1, CTLA-4, and TIM-3 genes were hypomethylated in tumor tissue, compared with normal tissue, but not significantly in LAG-3 promoter." (PMID 29983831, 2018). "In addition, a recent study performing single cell analyses of the tumor and the microenvironment in primary and metastatic UMs outlined genomic complexity, as well as revealing a different subset of CD8+ T cells expressing checkpoint marker LAG3 but not PD1 or CTLA4." (PMID 36497441, 2022). "The reason could be due to the presence of additional immune checkpoints, such as the lymphocyte activation gene 3 (LAG-3), T-cell immunoglobulin and mucin domain 3 (TIM-3), and T-cell immunoreceptor with Ig and ITIM domains (TIGIT), or lack of proper antigen presentation machinery in tumor cells." (PMID 36654598, 2022). "Eight other immune subsets, including naive CD4+ T cells, Lag-3+/−CD8+ T cells and CD14+macrophages, showed no significant enrichment in neither tumour groups, although CD27− B cells with unknown functions were also significantly enriched in tumours with low immune-ITH." (PMID 33431814, 2021).
cancer (917 papers, 2013 to 2026). A tumor composed of atypical neoplastic, often pleomorphic cells that invade other tissues. "Discrepant results have been described on the association of LAG-3 expression and patient outcome in different types of cancer." (PMID 41051510, 2025). "Pan-cancer analyses have discovered that HNSCC is characterized by elevated LAG-3 expression, which is significantly associated with adverse prognosis and resistance to therapeutics." (PMID 40994140, 2025). "These drugs, such as monoclonal antibodies that block CTLA-4 (cytotoxic T-lymphocyte-associated protein 4), LAG-3 (lymphocyte activation gene 3), and PD-1 or its ligand (PD-L1), restore T-cell immune responses in different cancer types." (PMID 39857724, 2025). "High expression of LAG-3 in various cancers is associated with impaired antitumor activity of the immune system, and blocking it with mAbs or small-molecular-weight inhibitors shows promise in immunotherapy." (PMID 40574024, 2025). "In patients with high-grade serous ovarian cancer (HGSOC), it was shown that circulating LAG-3 is associated with better survival in this cancer." (PMID 40649775, 2025). "Remarkably, in cancer patients the presence of high percentage of T cells co-expressing LAG-3 and PD-1 has been associated with dysfunctionality and resistance to PD-1 blockade-based immunotherapies." (PMID 41051510, 2025). "LAG-3 is one of the novel checkpoint molecules expressed by T cells, its expression on γδ T lymphocytes is linked with their exhaustion and dysfunction in cancer." (PMID 40136700, 2025). "Recently, LAG-3 has been identified as an important immune checkpoint in different cancer types, and its blockade has been associated with enhanced antitumor responses." (PMID 41303538, 2025). "YY1 regulates the protein stability and gene expression of many different cancer-associated genes, as well as the expression of LAG-3 directly at the promoter region." (PMID 39796650, 2024). "The first one was to extract PD-1/LAG-3 gene co-expression signatures from human cancers using multiomic data associated to T-cell functions." (PMID 39030301, 2024). "FGL1, a fibrinogen-like protein, is another crucial immunosuppressive ligand of LAG-3, inhibiting T-cell activation and associated with poor prognosis in cancers like HCC." (PMID 39684559, 2024). "This demonstrated the association of the PDCD1/LAG3 signature with potentially immunogenic “hot” cancers." (PMID 39030301, 2024). "Soluble PD-1, PD-L1, CD28 family of receptors, B7 ligands families, LAG3, etc. all have reported associations with cancer susceptibility." (PMID 39218939, 2024). "The PD-1/LAG-3 co-signature was linked to molecular and cellular functions, and diseases characteristic of immune dysfunctionality and cancer (Fig. EV2B,C)." (PMID 39030301, 2024). "PD-1/LAG-3 gene co-expression signatures were extracted from multiomic data associated to T-cell functions in human cancers, uncovering a PD-1/LAG-3 highly dysfunctional signature." (PMID 39030301, 2024). "Here we carried out thorough and systematic omic studies at multiple levels to identify the regulatory pathways that were activated/deactivated in PD-1/LAG-3+ cancer-associated T cells." (PMID 39030301, 2024). "The TISIDB database was utilized to explore the association between LAG3 expression and clinical stage and grade of cancers." (PMID 38277212, 2024). "Single-nucleotide polymorphisms (SNPs) in PD-1 and LAG-3 genes are linked to vulnerability and medical results in different types of cancer." (PMID 38792904, 2024). "The aim is to offer valuable perspectives for investigating the underlying mechanisms of LAG-3 in cancer treatment." (PMID 39252941, 2024). "Gal-3 is a recognised ligand of the lymphocyte activation gene-3 (LAG-3), an immune checkpoint receptor expressed on the surface of effector T cells and regulatory T cells, and associated with worse prognosis in several cancers." (PMID 37701441, 2023).
cancer (continued). "In humans, high levels of sLAG-3 are associated with a less favorable disease outcome in cancer, and the addition of recombinant Fc-bound LAG-3 (Fc-LAG-3) has an anti-apoptotic effect in vitro." (PMID 37287025, 2023). "LAG-3 is another important marker that overexpresses on TILs in a variety of cancers and is associated with disease prognosis; however, its prognostic impact is controversial." (PMID 36765348, 2023). "LAG3 expression was positively associated with immune cell infiltration and immune checkpoint genes in all of the cancers included." (PMID 38041068, 2023). "Lymphocyte-activation gene 3 (LAG3) is a recently discovered immune checkpoint molecule that has been linked to immunosuppression and the advancement of cancer in different types of solid tumors." (PMID 38041068, 2023). "LAG3 expression was negatively associated with activated dendritic cells (DC), activated mast cells, and eosinophils in most of the cancers included." (PMID 38041068, 2023). "The cytotoxic T-lymphocyte-associated antigen 4 (CTLA-4) and lymphocyte activation gene-3 (LAG-3) are similar kind of checkpoint proteins on immune cells which are used by cancer cells to bind and evade the immune cell signalling-mediated death." (PMID 38112935, 2023). "In vivo studies showed that NK cells from LAG-3 deficient mice show defects in the killing of specific cancer cells." (PMID 36077354, 2022). "Interrogation of the TGCA and METABRIC databases confirmed that high expression of IDO1 and LAG3 was associated with poor survival in luminal B cancers." (PMID 34359625, 2021). "LAG-3 expression has therefore also been associated to poor prognosis in various human cancers including HCC." (PMID 33805268, 2021). "The presence of these cells expressing high levels of PD-1, TIM-3 and LAG-3 was associated with resistance to cancer immunotherapy." (PMID 35069581, 2021). "NK cells have emerged as contributors to the effect of cytotoxic T lymphocyte-associated protein 4 (CTLA4), LAG3, and PD-1 in cancer patients, suggesting that immune checkpoint receptors regulate NK cell activity under pathological conditions." (PMID 34220833, 2021). "Among all the significant associations, CD36 expression was negatively correlated with ADORA2A and LAG3 in multiple cancer types, but positively associated with IDO1, IDO2, and KIR3DL1 in multiple cancers." (PMID 34234847, 2021). "Concluding, a deeper understanding of the basic mechanisms underlying LAG-3 intracellular signaling will provide insight for further development of novel strategies for cancer, infections, autoimmune disorders, and neurological diseases." (PMID 34067904, 2021). "We found that intratumoural lymphocytes expressing CD8, PD-1, FOXP3, TIM3, and LAG3, as well as PD-L1-expressing carcinoma cells, were each associated with better survival, independent from standard clinicopathologic factors." (PMID 33804486, 2021). "T cells expressing high levels of inhibitory receptors such as PD-1 and LAG-3 are a hallmark of chronic infections and cancer." (PMID 33519801, 2020). "This review will summarize current knowledge about the impact of the genetic variants of CTLA-4, PDCD1, PD-L1, BTLA, TIM-3, and LAG-3 on cancer risk." (PMID 33519815, 2020). "Frequency of genetic variants of CTLA-4, PDCD1, PD-L1, BTLA, HAVCR2, and LAG3 genes (in different human populations) for which the association with cancer risk has been investigated." (PMID 33519815, 2020). "LAG-3 is significantly associated with prognosis and clinicopathological characteristics in various types of cancer, and has synergistic effects with PD-1/PD-L1." (PMID 32762721, 2020). "Blocking LAG3 has been shown to be active in association with anti-PD-1 or anti-PD-L1 agents in cancer patients." (PMID 31434339, 2019). "For this reason, specific anti-LAG3 mAbs are currently under investigation in the attempt to reverse cancer-associated immunosuppression." (PMID 31623599, 2019).
cancer (continued). "Changes in immune response markers, such as reduced CD4+ T cells, impaired NK cell function, and immune checkpoint molecules like programmed cell death protein 1 (PD‐1), programmed death‐ligand 1 (PD‐L1), and lymphocyte activation gene 3 (LAG3), have been implicated in cancer progression." (PMID 40236776, 2025). "We also present bioinformatic analyses demonstrating the overexpression of LAG-3, YY1, and PD-L1 in various cancers, their associations with immune infiltrates, and the fact that when LAG-3 is hypermethylated in its promoter region it correlates with a better overall survival." (PMID 39796650, 2024). "The association between LAG-3 and the cancer microenvironment is nuanced." (PMID 38390331, 2024). "Hence, to define gene signatures associated to PDCD1/LAG3 co-expression in human cancers, we performed an extensive analysis of publicly available multiomics cancer data." (PMID 39030301, 2024). "Although much has been discovered on PD-1 functions and its blockade, the molecular effects of PD-1/LAG-3 co-blockade over PD-1/LAG-3-associated dysfunctional signatures in cancer cells and T-cells are largely unknown." (PMID 39030301, 2024). "Besides programmed cell death protein 1 (PD-1) and cytotoxic T-lymphocyte associated protein 4, LAG3 is the third inhibitory receptor as a target for promoting anti-cancer responses and immunotherapies." (PMID 39211038, 2024). "So, LAG3 rs870849 genetic variants may affect both the expression and structure of LAG3 and the occurrence or progression of cancer." (PMID 37131179, 2023). "LAG3, locating on chromosome 12 (12p13.32) and encoding a type 1 transmembrane protein, has been proved to be involved in immune regulation and clinical aggressiveness of cancer." (PMID 38115039, 2023). "But there is little research on the association between LAG3 rs870849 and the risk of cancer." (PMID 37131179, 2023). "Furthermore, pan-cancer bioinformatic analysis revealed that LAG3 was associated with genetic alterations, RNA methylation modification-related genes, genomic instability, immune checkpoint genes, and infiltration of immune cells." (PMID 38041068, 2023). "Furthermore, overexpression of LAG-3 was inferred to be one of the causes of poor response to PD-1(L1) ICIs in cancers." (PMID 33717059, 2021). "Yet, little is known about the mechanisms of action underlying LAG-3 blockade in cancer." (PMID 33925565, 2021). "However, inconsistent with the present results, the findings of other studies indicate a favorable association between high expression of LAG3 and cancer-specific survival, particularly of the ER-negative, HER2-positive, and basal-like subtypes." (PMID 34267742, 2021). "Instead, the purpose of cleavage is post-translational regulation of LAG3 as demonstrated in mice where non-cleavable LAG3 or metalloproteinase inhibitor impairs T cell immunity and in human cancer patients where a higher LAG3:ADAM10 ratio is associated with disease progression and poor prognosis." (PMID 33488626, 2020). "Therefore, LAG-3 is closely associated with cancer-specific T-cell dysfunction associated with PD-1 co-expression and could serve as a compensatory mechanism to overcome resistance to PD-1 blockade in patients." (PMID 40796887, 2025). "Therefore, we investigated a potential association of LAG3 with the cancer-immunity cycle in KIRC." (PMID 38277212, 2024). "In pathway analysis and cancer immune correlation analysis, we observed that SRSFs were associated with the activation or inhibition of multiple immune pathways, and were also closely related to the expression of multiple immune checkpoints (LAG3, CD274, CTLA4, TIGIT, PDCD1)." (PMID 38015716, 2023). "Thus, cancer immunotherapy targeting proteins including programmed cell death-1 (PD-1) and programmed cell death ligand-1 (PD-L1), lymphocyte activation gene 3 (LAG-3), and cytotoxic T-lymphocyte-associated antigen-4 (CTLA-4), proved to be effective in different types of cancers." (PMID 34771722, 2021).
cancer (continued). "A variety of immunoregulatory molecules are being explored in order to improve outcomes and overcome resistance to PD‐1/CTLA‐4/LAG‐3 checkpoint inhibition in cancer." (PMID 41474629, 2026). "PD-1 and LAG-3 are established markers of T-cell exhaustion in cancer and are co-expressed by stem-like CD8 T cells, a population critical for the response to anti-PD1 therapy, providing the rationale for their dual-blockade." (PMID 42284551, 2026). "The development of aptamers targeting TIM-3 and LAG-3 has opened new avenues in cancer immunotherapy." (PMID 40870970, 2025). "TIM-3 expression is significantly increased and often co-expressed with other IC receptors such as PD-1 or LAG-3 in the context of cancer and chronic infections." (PMID 40574024, 2025). "LAG3, as an emerging immune checkpoint target, holds significant development potential and broad market prospects in cancer immunotherapy." (PMID 40415479, 2025). "Soluble LAG‐3 correlates with enhanced T cell effector function, suggesting its potential as a prognostic indicator for cancers." (PMID 40415479, 2025). "Another innovative application involves using magnetic nanoparticles conjugated with LAG-3 aptamers for hyperthermia-based cancer treatment." (PMID 40870970, 2025). "Time resolved FRET tested small molecule inhibition of LAG-3 on T cells in relation to FGL1 on human cancers while nanosensors identified specific exosomes to try to diagnose cancer earlier." (PMID 40625731, 2025). "TIGIT, LAG3, PDCD1, and CXCL13 were highly associated with different stages of cancers, especially in KIRC and THCA." (PMID 40076932, 2025). "Further investigation of anti-CCR8 RIT as a potential cancer-agnostic agent and its combinations with other immunotherapy agents such as anti-PD-1, LAG3 or TIGIT is warranted." (PMID 41035646, 2025). "With advances in LAG-3 inhibitor research, it is possible to refine further therapeutic strategies that can increase the effectiveness of cancer treatment and improve patient prognosis." (PMID 40574024, 2025). "Consistent with murine studies, well-known Tex genes (CTLA4, LAG3, HAVCR2 (gene encoding Tim-3), PDCD1, TIGIT, TOX) were among the most prominently represented in Tex from human cancers." (PMID 40236693, 2025). "in 1990 on activated human NK and T cells, LAG-3 has gained attention as an immune checkpoint molecule and a key target in cancer immunotherapy." (PMID 40356928, 2025). "PD1/PDL1, CTLA-4, and LAG-3 are well-established inhibitory signaling axes in T cells in several cancers in animal models and patients, resulting in several FDA-approved therapies targeting these axes (immune checkpoint blockade; ICB)." (PMID 40723238, 2025). "Despite many gaps and controversies in LAG3 biology, it is a molecule of therapeutic interest, particularly in the cancer field." (PMID 40359031, 2025). "In cancers, T cells are persistently stimulated by antigens, leading to the continuous high expression of LAG3 along with other co-inhibitory receptors such as PD-1, CTLA-4, and TIM-3." (PMID 40861801, 2025). "LAG3, also known as CD223, is a potential cancer immunotherapeutic target because of its ability to mediate T-cell exhaustion." (PMID 41551611, 2025). "Further analyses showed that these high HLA‐DR+ cancer cell tumors exhibited elevated levels of LAG3, TNFRSF9, CTLA4, PDCD1, TIGIT, ITGB2, and GZMB." (PMID 40464412, 2025). "One is the breakdown of immune tolerance to the heart mediated by the CTLA-4, PD-1, and LAG-3 pathways, and the other involves the expansion of T cells targeting a common antigen shared by the cancer and the heart." (PMID 40547024, 2025). "Several mAbs targeting LAG3 with either antagonistic, depleting, or agonistic activities have been developed and are currently in clinical trials for patients with cancer and autoimmune illnesses." (PMID 40359031, 2025).